NCKAP1 (NCK associated protein 1)
Description:
Part of the WAVE complex that regulates lamellipodia formation. The WAVE complex regulates actin filament reorganization via its interaction with the Arp2/3 complex. Actin remodeling activity is regulated by RAC1. As component of the WAVE1 complex, required for BDNF-NTRK2 endocytic trafficking and signaling from early endosomes.
Synonyms: HEM2; NAP1; NAP125; p125Nap1
Tractability: Small molecule: a structure with a bound ligand is known; it has a high-quality binding pocket. Antibody: UniProt places it where antibodies can reach, with medium confidence; UniProt predicts a signal peptide or a membrane-spanning region; its Gene Ontology location is reachable by antibodies, with medium confidence. PROTAC: ubiquitination databases record sites on it; its protein half-life has been measured.
Gene: Protein-coding gene on chromosome 2 (182,909,115 to 183,038,858, reverse strand). Ensembl gene ENSG00000061676.
Subcellular location: Cell membrane; Cell projection, lamellipodium membrane
Subcellular location (Human Protein Atlas): Cytosol
Pathways (Reactome):
Signal Transduction: RAC1 GTPase cycle; RAC2 GTPase cycle; RAC3 GTPase cycle; RHO GTPases Activate WASPs and WAVEs; VEGFA-VEGFR2 Pathway
Disease: FCGR3A-mediated phagocytosis
Immune System: Regulation of actin dynamics for phagocytic cup formation
Gene Ontology:
Molecular function: protein binding; small GTPase binding
Biological process: positive regulation of Arp2/3 complex-mediated actin nucleation; positive regulation of lamellipodium assembly; Rac protein signal transduction; apoptotic process; cell migration; central nervous system development; cortical actin cytoskeleton organization; neuron projection morphogenesis; positive regulation of actin filament polymerization
Cellular component: extracellular exosome; focal adhesion; SCAR complex; cytosol; filamentous actin; lamellipodium; plasma membrane; ruffle; lamellipodium membrane; postsynapse
Genetic constraint (gnomAD): Loss-of-function variants: 6 observed, 84.79 expected, observed/expected ratio (o/e) 0.0708, 90% interval 0.038 to 0.14. The upper end of that interval is the gene's LOEUF score, 0.14, which puts it in group 1 of 6, group 1 being the genes least tolerant of losing a copy. Missense variants: 644 observed, 971.33 expected, observed/expected ratio (o/e) 0.66, 90% interval 0.62 to 0.71. Synonymous variants: 333 observed, 329.13 expected, observed/expected ratio (o/e) 1.01, 90% interval 0.92 to 1.11.
Gene-disease validity (ClinGen):
ClinGen rates the evidence that NCKAP1 causes each of these diseases.
complex neurodevelopmental disorder (autosomal dominant): Definitive. A disorder that involves more than one phenotype associated with the central nervous system, including but not limited to intellectual disability, autism, and seizures (epilepsy).
Homologues: Orthologues: chimpanzee NCKAP1 (100% identical), macaque NCKAP1 (100% identical), rabbit NCKAP1 (99% identical), dog NCKAP1 (99% identical), pig NCKAP1 (99% identical), mouse Nckap1 (99% identical), rat Nckap1 (99% identical), tropical clawed frog nckap1 (98% identical), guinea pig NCKAP1 (97% identical), zebrafish nckap1 (96% identical), Drosophila melanogaster Hem (60% identical), Caenorhabditis elegans gex-3 (41% identical). Paralogues in human: NCKAP1L (59% identical).
Diseases named in the same sentence as NCKAP1 in open-access papers:
NCKAP1 is named in the same sentence as 64 diseases in open-access papers, as found by Europe PMC text mining. Sharing a sentence is not in itself a finding about the gene and the disease. The quoted sentences say what the papers report.
breast carcinoma (11 papers, 2021 to 2025). "A single-factor analysis of breast cancer showed that the high expression of NCKAP1 was strongly associated with poor metastasis-free survival of breast cancer patients, suggesting that NCKAP1 is an independent prognostic factor of breast cancer." (PMID 38625593, 2025). "In breast cancer, the overexpression of NCKAP1 is associated with poor prognosis, indicating that it may play a role in the malignancy and prognosis of breast cancer." (PMID 38625593, 2025). "High expression level of NCKAP1 is associated with poorer survival in breast cancer patients." (PMID 34759953, 2021). "The crucial role of NCKAP1 in balancing cell death and survival underscores its importance in tumor biology and its involvement in breast cancer metastasis as well as in colon and lung cancers, making it a promising target for cancer therapy." (PMID 40141455, 2025). "To further figure out the underlying molecular mechanisms, we performed bulk RNA-seq with breast cancer MCF7 cell lines of control, as well as deficient of PIP5K1A, NCKAP1, or CYFIP1." (PMID 39408874, 2024). "The high expression of disulfidptosis genes (e.g., SLC3A2, RPN1, BRK1, ACTR2, ACTR3, SLC7A11, and NCKAP1) in the KM analysis of breast cancer indicated the poor prognosis of patients." (PMID 38035071, 2023). "Overexpression of NCKAP1 also increased the invasion potential of breast cancer cells, in addition to the levels of Rac1 in the WASF3 immunocomplex, suggesting NCKAP1 acts to enhances Rac1 engagement." (PMID 33467681, 2021). "A previous study showed that the WASF3 gene is a promoter of cell invasion in breast cancer and the Nckap1 can keep WASF3 in an inactive conformation through binding to the WASF homology domain at the N-terminus." (PMID 34917619, 2021). "Lower levels of NCKAP1 mRNA and protein in ACNA cells correlate with increased growth and colony formation, whereas NCKAP1 silencing disrupts the WASF3 complex and inhibits breast cancer progression." (PMID 40141455, 2025). "In conclusion, we demonstrate that multiple genes, including PIP5K1A, NCKAP1, and CYFIP1, are effective targets for enhancing MHC-I expression in breast cancer cells." (PMID 39408874, 2024). "Through bioinformatics analysis, we found that PIP5K1A, NCKAP1, and CYFIP1 are highly expressed in breast cancer tumors compared with normal tissues, and higher expression of these genes is correlated with a worse prognosis in breast cancer patients." (PMID 39408874, 2024). "Furthermore, we verified partially according to KEGG functional enrichment or gene-dependency analysis and figured out multiple genes, including PIP5K1A, NCKAP1, CYFIP1, DIS3, TBP, and EXOC1, as effective gene targets for increasing MHC-I expression in breast cancer." (PMID 39408874, 2024). "Thus, the downregulation of NCKAP1 inhibits the activity of WASF3 and may suppresses metastasis in breast cancer cells." (PMID 34917619, 2021).
hepatocellular carcinoma (7 papers, 2019 to 2024). A malignant tumor that arises from hepatocytes. "NCKAP1 has been shown to be associated with cancer metastasis in non-small cell lung carcinoma, hepatocellular carcinoma, autism, and Alzheimer’s disease." (PMID 35951140, 2022). "In our previous report, we identified miR-34c-3p as an independent factor contributing to the carcinogenesis of hepatocellular carcinoma (HCC) by targeting NCK Associated Protein 1 (NCKAP1)." (PMID 31068575, 2019). "NCKAP1, as a tumor inhibitor gene in hepatocellular carcinoma, can improve the prognosis of liver cancer patients by targeting Rb1/p5321." (PMID 38166898, 2024). "Currently, NCKAP1 is reported to be involved in poor prognosis and metastasis in hepatocellular carcinoma (HCC), breast cancer, and non-small-cell lung cancer (NSCLC)." (PMID 36639705, 2023).
autism (6 papers, 2017 to 2025). Persistent deficits in social interaction and communication and interaction as well as a markedly restricted repertoire of activity and interest as well as repetitive patterns of behavior. "However, the phenotypic overlap and the fact that the variant was identified as de novo constituted sufficient evidence for disease causality, so that the case could be considered solved, further validating NCKAP1 as a causative gene for neurodevelopmental disorders and autism." (PMID 36553572, 2022). "Importantly, all molecules changed in the striatal Shank3Δ11-/- mutant PSD that matched with the SFARI autism gene database were reduced and comprised the murine homologs of proteins encoded by several major ASD candidates including NCKAP1, GRIN2B and TRIO, 3 of the 65 high-risk ASD TADA genes." (PMID 28261056, 2017). "Only TNRC6B, NCKAP1, and one of the two ZNF292 LGD DNMs occur in autism patients with an IQ in the normal range." (PMID 30564305, 2018).
renal clear cell carcinoma (6 papers, 2022 to 2025). "NCKAP1 was found to inhibit the malignant behavior of renal clear cell carcinoma cells in studies of renal clear cell carcinoma, suggesting its potential as a prognostic biomarker for screening patients in clinical practice." (PMID 40295497, 2025). "In contrast, reduced NCKAP1 expression in renal clear cell carcinoma (KIRC), kidney renal papillary cell carcinoma (KIRP), kidney chromophobe renal cell carcinoma (KICH), and prostate adenocarcinoma (PRAD) was also identified." (PMID 40141455, 2025). "Furthermore, decreased NCKAP1 expression in individuals with hepatocellular carcinoma is correlated with unfavorable prognosis and adverse patient outcomes in clear cell renal cell carcinoma (ccRCC)." (PMID 40141455, 2025). "Moreover, NCKAP1 significantly inhibited cell proliferation, invasion and migration in clear cell renal cell carcinoma and is a prognostic biomarker for clinical application." (PMID 38230212, 2024). "Renal clear-cell carcinoma shows a positive correlation with immune cells in relation to NCKAP1." (PMID 38223725, 2024).
Intellectual disability (4 papers, 2019 to 2025). "NCKAP1 also interacts directly with CYFIP2, which has been linked to intellectual disability and ASD." (PMID 40551827, 2025). "The proband’s phenotype, including intellectual disability, speech delay, global developmental delay, repetitive behaviors, and CHD, is consistent with the phenotypic spectrum associated with pathogenic NCKAP1 variants." (PMID 41462819, 2025). "A possible association between NCKAP1 (HGNC:7666) and intellectual disability has already been proposed in 2017, while subsequent studies have further supplemented evidence for this gene–disease association through the collection of larger cohorts." (PMID 36553572, 2022).
Alzheimer disease (3 papers, 2019 to 2023). A progressive, neurodegenerative disease characterized by loss of function and death of nerve cells in several areas of the brain leading to loss of cognitive function such as memory and language. "NCKAP1 was first discovered in patients with Alzheimer’s disease (AD), which has been proved to drive metastasis in human non-small-cell lung cancer." (PMID 38052924, 2023).
autism spectrum disorder (3 papers, 2024 to 2025). A spectrum of developmental disorders that includes autism, and Asperger syndrome. "Two components of it (CYFIP2 and NCKAP1) are encoded by genes whose genetic mutations increase the risk for autism spectrum disorder (ASD) and related neurodevelopmental disorders." (PMID 39660913, 2025). "We describe a 43-year-old man with neurodevelopmental disorder (NDD) with features of autism spectrum disorder (ASD) due to a rare pathogenic variant in the NCKAP1 gene." (PMID 40551827, 2025). "Disruptive variants of NCKAP1 have been associated with neurodevelopmental disorders, including Coffin-Siris syndrome 1 (CSS1) and autism spectrum disorder (ASD)." (PMID 38349741, 2024).
gastric cancer (3 papers, 2025). A primary or metastatic malignant neoplasm involving the stomach. "Similar results were observed in gastric cancer, where NCKAP1 emerged as a promising prognostic biomarker correlated with actin dynamics, GTPase energy metabolism, immune infiltration, and immunotherapy." (PMID 40141455, 2025). "Experimental studies are needed to correlate the role of NCKAP1 in gastric cancer, which may affect the progression of gastric cancer through disulfidptosis." (PMID 40295497, 2025). "At present, there have been no reports on the relationship between NCKAP1 and gastric cancer." (PMID 38625593, 2025).
glioma (3 papers, 2024 to 2025). A benign or malignant brain and spinal cord tumor that arises from glial cells (astrocytes, oligodendrocytes, ependymal cells). "Univariate Cox regression analysis has discerned significant associations between glioma patient survival trajectories and the expression profiles of several disulfidptosis-related genes, specifically SLC3A2, RPN1, NCKAP1, and SLC7A11 (all, P < 0.05)." (PMID 38977800, 2024). "Notably, regulatory proteins such as SLC7A11 and NCKAP1, critical in disulfidptosis, also play essential roles in glioma onset and progression." (PMID 38504986, 2024). "GYS1, NDUFA11, OXSM, RPN1, and SLC3A2 play a role in promoting cancer in glioma, while LRPPRC, NCKAP1, NDUFS1, NUBPL and SLC7A11 play a role in inhibiting tumour." (PMID 39993959, 2025). "Spearman correlation analyses were employed to elucidate the interplay between SLC3A2, RPN1, NCKAP1, and SLC7A11 within the glioma landscape, revealing the strongest correlation between SLC3A2 and SLC7A11 (R = 0.242, P < 0.001)." (PMID 38977800, 2024).
melanoma (3 papers, 2022 to 2025). A malignant, usually aggressive tumor composed of atypical, neoplastic melanocytes. "In melanoma, NCKAP1 inhibition can slow tumor proliferation and growth, highlighting its role in cell cycle progression." (PMID 40141455, 2025). "In mammals, RNAi mediated knockdown of NCKAP1 (HEM2) in a melanoma cell line revealed that HEM2 is important for Rac-dependent formation of structures called lamellipodia in response to growth factor stimulation." (PMID 39026677, 2024).
stomach adenocarcinoma (3 papers, 2024 to 2025). "NCKAP1 is a target gene of miR383-5p, and miR383-5p could be a valuable therapeutic target for stomach adenocarcinoma." (PMID 38625593, 2025). "We demonstrated elevated expression levels of NCKAP1 in multiple cancer types, including cholangiocarcinoma (CHOL), head and neck squamous cell carcinoma (HNSC), liver hepatocellular carcinoma (LIHC), and stomach adenocarcinoma (STAD)." (PMID 40141455, 2025).
bladder cancer (2 papers, 2023 to 2025). "The expression level of NCKAP1 protein is closely associated with the histological tumor grade, metastasis, and low survival rate of various cancer patients.In bladder cancer (BLCA), the prognostic value of PD-L1 expression is well-established." (PMID 37152941, 2023). "Our study has identified four disulfidptosis suppressor genes, namely SLC7A11, SLC3A2, RPN1, and NCKAP1, which play significant roles in the development and immune infiltration of bladder cancer." (PMID 37152941, 2023).
cervical squamous cell carcinoma (2 papers, 2024 to 2025). A squamous cell carcinoma arising from the cervical epithelium. "Specifically, high NCKAP1 expression correlated with poor survival in adrenocortical carcinoma (ACC, p = 0.061), cervical squamous cell carcinoma (CESC, p = 0.020), and LIHC (p = 0.037) patients, indicating that NCKAP1 may serve as an adverse prognostic factor in those cancer types." (PMID 40141455, 2025).
liver cancer (2 papers, 2021 to 2024). An epithelial or non-epithelial malignant neoplasm that arises from the liver. "The function of NCKAP1 in liver cancer has recently been clarified." (PMID 34917619, 2021).
lung carcinoma (2 papers, 2023 to 2024). "The expression levels of NCKAP1 and GYS1 were examined in both lung cancer and normal alveolar epithelial cells." (PMID 38223725, 2024). "To investigate the functional roles of NCKAP1 and GYS1, we conducted experiments using the human lung cancer H460 cell line with knockdown of NCKAP1 and GYS1." (PMID 38223725, 2024). "As a result of the mRNA levels in the blood from two lung cancer PDX cases and two colon cancer PDX cases, significance was found only for NCKAP1 and MCTP1." (PMID 36639705, 2023). "The impact of SLC7A11 and SLC3A2 on the prognosis of lung cancer have been documented, it is still uncertain whether NCKAP1 and GYS1 influence the prognosis in lung cancer remains unclear." (PMID 38223725, 2024). "However, the expression and role of NCKAP1 and GYS1 in lung cancer remain unclear." (PMID 38223725, 2024).